RNU6-595P (RNA, U6 small nuclear 595, pseudogene)
Gene: Small nuclear RNA gene on chromosome 12 (62,334,091 to 62,334,197, reverse strand). Ensembl gene ENSG00000200814.
Homologues: Orthologues: chimpanzee U6 (99% identical), macaque U6 (87% identical), rabbit U6 (59% identical). Paralogues in human: RNU6-43P (79% identical), RNU6-333P (78% identical), RNU6-34P (78% identical), RNU6-658P (78% identical), RNU6-880P (78% identical), RNU6-1122P (77% identical), RNU6-11P (77% identical), RNU6-140P (77% identical), RNU6-235P (77% identical), RNU6-25P (77% identical), RNU6-33P (77% identical), RNU6-37P (77% identical), and 1284 more.